SPHK2 (sphingosine kinase 2)
Diseases named in the same sentence as SPHK2 in open-access papers (continued):
Sharing a sentence is not in itself a finding about the gene and the disease.
metabolic dysfunction-associated steatotic liver disease (3 papers, 2023 to 2025). Metabolic dysfunction-associated steatotic liver disease (MASLD, formerly known as nonalcoholic fatty liver disease or NAFLD) is a type of liver disease that is not caused by alcohol. "Immunohistochemical staining revealed decreased SphK2 protein levels within regions proximal to hepatic lipid accumulation in individuals diagnosed with metabolic dysfunction-associated steatotic liver disease (MASLD)." (PMID 40200091, 2025).
papillary thyroid carcinoma (3 papers, 2020 to 2022). "Our results were in consistent with a previous study that reported that upregulation of SphK2 partially increased the migration of papillary thyroid carcinoma cells." (PMID 33968977, 2021). "lncRNA LINC00520 accelerates the progression of papillary thyroid carcinoma by serving as a competing endogenous RNA of microRNA-577 to increase SphK2 expression." (PMID 33113852, 2020).
steatosis (3 papers, 2019 to 2022). Increased lipid within the cytoplasm of cells. "Comparable levels of steatosis were found in the parenchyma of WT and Sphk2-KO livers using hematoxylin and eosin (H&E) staining." (PMID 36333295, 2022). "Importantly, a significant increase of SPHK2 expression was found in both steatosis and steatohepatitis cases of multiple patients." (PMID 30718751, 2019). "In addition, SPHK2 knockout mice characterized rapid development of steatosis after 2 weeks of HFD, pointing out that SPHK2 and also generated S1P can determine the activity of enzymes and receptors that regulate the lipid metabolism." (PMID 34830360, 2021).
acute myeloid leukemia (2 papers, 2023). Acute myeloid leukemia (AML) is a group of neoplasms arising from precursor cells committed to the myeloid cell-line differentiation. "Thus, inhibition of SPHK1 in human acute myeloid leukemia cells, but not the inhibition of SPHK2, induces MCL-1 degradation." (PMID 37020867, 2023).
alcoholic fatty liver disease (2 papers, 2020 to 2021). Lipid infiltration of the hepatic parenchymal cells that is due to alcohol abuse. "Intriguingly, SphK2 is likely a metabolically protective factor in the liver, as Sphk2−/− predisposes to non-alcoholic and alcoholic fatty liver diseases, whereas adenoviral overexpression of SphK2 primarily in the liver improves insulin resistance." (PMID 34530846, 2021). "Sphk2−/− also appears to predispose mice to alcoholic fatty liver disease." (PMID 32917816, 2020).
Autoimmunity (2 papers, 2013 to 2018). The occurrence of an immune reaction against the organism's own cells or tissues. "Furthermore, we found that heterozygous and homozygous carriers of the risk alleles rs12150079 (ORMDL3) and rs33988101 (SPHK2) had lower levels of T cell autoimmunity (p = 0.042 and p = 0.017, respectively)." (PMID 29671030, 2018). "FTY720 (2-amino-2-[2-(4-octylphenyl)ethyl]propane-1,3-diol; Fingolimod, Novartis), a synthetic sphingosine analogue of myriocin, regulates sphingosine-1-phosphate receptor signalling and suppresses autoimmunity upon its phosphorylation by sphingosine kinase-2 (SK-2)." (PMID 23180565, 2013).
bladder cancer (2 papers, 2022 to 2024). "In this study, we performed bioinformatic analyses of bladder cancer database and unveiled significant high expression of SPHK1 but not SPHK2 with clinical BS subtype, a typically invasive cancer, or LI subtype that is associated with chemo resistant." (PMID 39284838, 2024).
brain injury (2 papers, 2020 to 2025). Acute and chronic (see also brain INJURIES, CHRONIC) injuries to the brain, including the cerebral hemispheres, CEREBELLUM, and brain STEM. "Moreover, COX contributed to neuronal plasticity after traumatic brain injury (TBI), and it has been reported that TBI decreased the expression of sphingosine kinase 2 (SphK2), the complex of neutral ceramidase and COX subunit 1(COX-1), thereby further influencing mitochondrial function." (PMID 32754029, 2020).
cervical carcinoma (2 papers, 2018 to 2022). A carcinoma arising from either the exocervical squamous epithelium or the endocervical glandular epithelium. "Together, we suggest that targeting SphK2 by ABC294640 inhibits human cervical carcinoma cell growth in vitro and in vivo." (PMID 29416779, 2018). "We demonstrated that SphK2 is over-expressed in primary and established human cervical carcinoma cells." (PMID 29416779, 2018). "ABC294640, the novel, specific and competitive SphK2 inhibitor, in-activated SphK in cervical carcinoma cells, leading to S1P depletion, ceramide production and STAT3 inhibition." (PMID 29416779, 2018). "The SphK2 inhibitor also induced G1-S arrest and apoptosis in cervical carcinoma cells." (PMID 29416779, 2018). "First, we tested the expression of SphK2 in human cervical carcinoma cells." (PMID 29416779, 2018). "The results of this current study proposed that SphK2 could be a novel oncotarget protein and rational therapeutic target for human cervical carcinoma." (PMID 29416779, 2018).
chronic kidney disease (2 papers, 2018 to 2022). Impairment of the renal function secondary to chronic kidney damage persisting for three or more months. "Furthermore, these data suggest that selective inhibition of Sphk2 is an attractive new option to enhance Epo synthesis and thereby to reduce anemia development in chronic kidney disease." (PMID 35682566, 2022).
Cognitive impairment (2 papers, 2024 to 2026). Abnormal cognition is characterized by deficits in thinking, reasoning, or remembering. "However, SphK2 KO J20 mice showed hippocampal volume loss, myelin loss, and cognitive impairment; therefore, the possibility of adverse effects should be considered." (PMID 38280459, 2024). "DSS improved VaD cognitive impairment by modulating sphingolipid metabolism and promote myelin regeneration via activating the SPHK2/S1P/S1PR5 signaling pathway." (PMID 41495814, 2026). "Co-administration of SPHK2 inhibitor ABC294640 significantly diminishes the improvement of DSS on cognitive impairment as well as sphingolipid metabolism in VaD rats." (PMID 41495814, 2026).
colonic adenocarcinoma (2 papers, 2017 to 2020). "Our study provides compelling evidence to support diverse roles for Sphk2 in colonic adenocarcinoma cells resistance to ATRA therapy." (PMID 28465486, 2017).
colorectal tumor (2 papers, 2022). "The colorectal tumors that were developed in Sphk2−/− mice showed great sensitivity to 5-FU therapy, indicating that high SPHK2 expression in colorectal tumors yields resistance to 5-FU chemotherapy treatment." (PMID 35565311, 2022).
Huntington disease (2 papers, 2021 to 2025). Huntington disease (HD) is a rare neurodegenerative disorder of the central nervous system characterized by unwanted choreatic movements, behavioral and psychiatric disturbances and dementia. "In a model of Huntington disease (HD), SPHK2 is hyperphosphorylated in brain samples from symptomatic mice." (PMID 34055895, 2021).
kidney carcinoma (2 papers, 2013 to 2021). Primary or metastatic malignant neoplasm involving the kidney. "Similar to the results observed in human renal cancer cells, the ablation of SphK2 decreased TNBC cell migration." (PMID 33968977, 2021). "However, Gao and Smith (2011) reported contrasting results in which knockdown of SphK2 led to increased S1P production in renal carcinoma cells owing to the elevated expression of SphK1." (PMID 33968977, 2021). "Accordingly, it has recently been found that chemical inhibition of sphingosine kinase 2 induces the formation of autophagosomes while promoting nonapoptotic cell death in human kidney carcinoma cells." (PMID 23894595, 2013).
liver cancer (2 papers, 2018 to 2025). An epithelial or non-epithelial malignant neoplasm that arises from the liver. "Recent studies have revealed the unique role of SphK2 in liver cancer therapy." (PMID 41234914, 2025). "Among several key enzymes regulating the levels of ceramide, sphingosine and S1P, SphK1 but not SphK2 mRNA expression was significantly increased in DEN-induced liver cancer tissues compared with liver tissues without DEN treatment." (PMID 29643998, 2018).
lymphopenia (2 papers, 2011 to 2015). Reduction in the number of lymphocytes. "While many studies including the results presented here strongly support a role for SphK1 in cellular functions such motility and collagen production, a recent report suggests that SphK2 deficiency contributes to reduced S1P accumulation in lymphoid tissues and attenuated T and B cell lymphopenia." (PMID 21304987, 2011). "The role of SPHK2 in FTY720 drug action was supported by lack of lymphopenia in SPHK2 knockout mice with FTY720 whereas administration of FTY720P caused lymphopenia in this knockout model." (PMID 26513477, 2015).
melanoma (2 papers, 2018 to 2021). A malignant, usually aggressive tumor composed of atypical, neoplastic melanocytes. "Therefore, our findings indicate that Sphk1 inhibition and Sphk2 activation are important for cisplatin mediated apoptosis in PKCδ deficient B16F10 melanoma cell." (PMID 30701020, 2018). "Sphk1 and Sphk2 maintained a reciprocal regulation in PKCδ silenced B16F10 melanoma cells in a time dependent manner, which was found to be correlated with the activity assay of sphingosine kinases." (PMID 30701020, 2018).
non-alcoholic steatohepatitis (2 papers, 2022 to 2025). "Experimental models further indicate that dysregulation of SphK2 directly induces NAFLD and participates in the carcinogenic process associated with non-alcoholic steatohepatitis (NASH) through S1P-mediated epigenetic reprogramming." (PMID 41234914, 2025). "Given the importance of FC in non-alcoholic steatohepatitis (NASH) and HCC, the role of SphK2 in hepatic cholesterol homeostasis should be investigated in further studies." (PMID 36333295, 2022).
osteoarthritis (2 papers, 2013 to 2024). A noninflammatory degenerative joint disease occurring chiefly in older persons, characterized by degeneration of the articular cartilage, hypertrophy of bone at the margins and changes in the synovial membrane. "On the other hand, ABC29460, a selective inhibitor of sphingosine kinase 2, an enzyme that converts sphingosine to S1P, attenuated cartilage damage and reduced chondrocyte apoptosis in a rat model of osteoarthritis." (PMID 23638138, 2013).
pneumonia (2 papers, 2019 to 2021). An acute, acute and chronic, or chronic inflammation focally or diffusely affecting the lung parenchyma, caused by an infection in one or both of the lungs (by bacteria, viruses, fungi, or mycoplasma.). "Our genomic data suggests a potential role for SPHK2 in PA-induced pneumonia through elevated expression of inflammatory genes in lung tissue." (PMID 31842752, 2019). "Our results show that SPHK2/S1P signaling cascade mediating PA-induced pneumonia modulates signaling events related to extracellular matrix remodeling, interleukin (IL) signaling, and complement cascade in the host lung." (PMID 31842752, 2019). "We suggest that the biological phenomenon of reduced intensity of PA pneumonia in the Sphk2 KO mice could involve multiple pathways and the significant ones identified in our analyses is presented here." (PMID 31842752, 2019). "The objective of this study is to identify novel pathways related to SPHK2/S1P signaling, that could contribute to the pathology as well as protection of PA-induced pneumonia." (PMID 31842752, 2019). "Thus, targeting SPHK2/S1P signaling in PA-induced lung inflammation could serve as a potential therapy to combat PA-induced pneumonia." (PMID 31842752, 2019).
primary effusion lymphoma (2 papers, 2014 to 2022). A large B-cell lymphoma located in the body cavities, characterized by pleural, peritoneal, and pericardial fluid lymphomatous effusions and that is always associated with human herpes virus-8 (HHV-8). "We have recently reported that targeting SphK2 induces apoptosis for human primary effusion lymphoma (PEL) cell lines infected by the Kaposi’s sarcoma-associated herpesvirus (KSHV), and this occurs in part through inhibition of canonical NF-κB activation." (PMID 25010828, 2014).
retinal degeneration (2 papers, 2019). Degeneration of the retina. "In the present study, we used Sphk2 KO mice to determine if FTY720 requires phosphorylation to FTY720-P prior to assuming its protective role in retinal degeneration." (PMID 31123291, 2019). "As pigmented mice are resistant to light-induced retinal degeneration and unsuitable for our model, we generated an albino Sphk2 KO line by 7-generation backcrossing with Balbc mice." (PMID 31123291, 2019). "Second, we examined the role of SphKs in light-induced retinal degeneration only with a SphK inhibitor that was not selective for SphK1 or SphK2." (PMID 31357484, 2019).
thrombosis (2 papers, 2017 to 2021). "Previous studies showed that impaired platelet S1P synthesis in SphK2 deficient mice protected mice from in vivo arterial thrombosis, without associated bleeding, indicating a role for S1P in thrombosis, likely through an effect on S1PR113." (PMID 34321503, 2021). "Massberg and colleagues provide evidence demonstrating SphK2 expression, regulates platelet aggregation and that deletion of SphK2 leads to reduced arterial thrombosis after vascular injury, suggesting SphK2 is a potentially important target for protection against arterial thrombosis." (PMID 28415564, 2017).
anemia (1 paper, 2022). A reduction in the number of red blood cells, the amount of hemoglobin, and/or the volume of packed red blood cells. "Remarkably, our data suggest that loss or inhibition of Sphk2 can on the one side reduce fibrosis and thereby reduce the speed of anemia development, and on the other side can also actively increase Epo synthesis." (PMID 35682566, 2022). "Most importantly, our data suggest that Sphk2 is an attractive novel pharmacological target to upregulate Epo synthesis, which may be useful to prevent anemia in CKD patients." (PMID 35682566, 2022).
Arterial thrombosis (1 paper, 2020). The formation of a blood clot inside an artery. "The integrity of thrombus formation was shown to be dependent on SphK2 activation of S1P in a mouse model, where deficiency in SphK2 resulted in defective platelet aggregation and arterial thrombosis." (PMID 33003377, 2020).
autoimmune disease (1 paper, 2025). A disorder resulting from loss of function or tissue destruction of an organ or multiple organs, arising from humoral or cellular immune responses of the individual to their own tissue constituents. "S1P, synthesized by SPHK2, regulates immune cell trafficking, inflammation, and oxidative stress, all of which are central to autoimmune diseases like vitiligo." (PMID 40856249, 2025).
bacteremia (1 paper, 2016). "However, the bacterial counts in the brains of SphK2−/− mice were significantly lower than those in the brains of wild-type mice, indicating that deletion of SphK2 resulted in decreased E. coli penetration into the brain without affecting the magnitude of bacteremia." (PMID 27711202, 2016).
breast tumor (1 paper, 2017). "A SphK2-deficient MCF-7 breast tumor xenograft mouse model study suggested a role of S1P, generated by SphK2, in early tumor development affecting macrophage polarization." (PMID 29269995, 2017). "Our recent study suggested that nuclear FTY720-P generated from SphK2, acting as a class I HDAC inhibitor, epigenetically reexpressed ERα and increased therapeutic sensitivity of ERα-negative syngeneic breast tumors to tamoxifen, indicating that FTY720 could be a useful anticancer drug." (PMID 29269995, 2017).
cervical adenocarcinoma (1 paper, 2023). An adenocarcinoma arising from the cervical epithelium. "However, this was in contrast with a study of human cervical adenocarcinoma cells which revealed that EGF/EGF receptors increased S1P production by activating Sphk2 within the endoplasmic reticulum or Golgi apparatus." (PMID 37038210, 2023).
cholelithiasis (1 paper, 2025). The presence of crystallized deposits forming in the gallbladder or biliary tree, primarily composed of cholesterol, bilirubin, and bile. "Specifically, genetically predicted higher levels of CROT (OR = 1.08, 95% CI = 1.04–1.12) were positively associated with an increased risk of cholelithiasis, while higher levels of SPHK2 (OR = 0.75, 95% CI = 0.65–0.86) were associated with a decreased risk of cholelithiasis." (PMID 40958306, 2025).
Crohn disease (1 paper, 2018). A gastrointestinal disorder characterized by chronic inflammation involving all layers of the intestinal wall, noncaseating granulomas affecting the intestinal wall and regional lymph nodes, and transmural fibrosis. "In addition, pharmacological inhibition of Sphk2 results in anti-inflammatory effects in a number of murine disease models including ulcerative colitis, Crohn’s disease and inflammatory arthritis, implying that reduced Sphk2 activity attenuates inflammation and injury in agreement with our findings." (PMID 29518138, 2018).
E. coli infection (1 paper, 2016). "Taken together, our findings thus far support the concept that meningitic E. coli infection of HBMEC increases the generation of S1P through SphK2 activation, and that the interaction of S1P with S1P2 is involved in E. coli invasion of the BBB." (PMID 27711202, 2016). "Our data demonstrate for the first time a novel role of S1P and a potential crosstalk between EGFR and SphK2-S1P-S1P2 signaling in HBMEC upon meningitic E. coli infection." (PMID 27711202, 2016).
emphysema (1 paper, 2023). "To investigate the mechanism underlying SphK2-mediated pulmonary emphysema, remodeling, and inflammation, we analyzed the effect of SphK2 deficiency on protein expression of CFTR." (PMID 36226596, 2023). "In our study, genetic deletion of SphK2 also contributed to emphysema-like changes following chronic CS exposure." (PMID 36226596, 2023). "Indeed, decreased α-SMA positive cells around the small airways and less severe emphysema were observed in SphK2−/− mice." (PMID 36226596, 2023). "Therefore, our observation indicates that the therapeutic intervention of SphK2/S1P signaling pathway may be effective in the early treatment of emphysema but may not be applicable to the research and treatment of end-stage COPD." (PMID 36226596, 2023).
fibrosis (1 paper, 2023). the formation of excess fibrous connective tissue in an organ or tissue in a reparative or reactive process. "In a SphK2 knockout (SphK2−/−) mouse model, we revealed that CS-induced pulmonary inflammation and fibrosis were significantly decreased, and SphK2 deficiency rescued CFTR activity and preserved pulmonary function by suppressing the S1P secretion." (PMID 36226596, 2023).
gastric ulcer (1 paper, 2014). An ulcerated lesion in the mucosal surface of the stomach. "We also found that the deficiency of SphK1(not SphK2) significantly inhibits gastric ulcer, indicating that SphK1 may play a pivotal role in gastric ulcer." (PMID 24454691, 2014).
Genetic obesity (1 paper, 2019). "Drosophila that lack sphingosine kinase 2 (Sk2) have served as a model of genetic obesity and lipotoxic cardiomyopathy." (PMID 31221967, 2019).
head and neck cancer (1 paper, 2013). A primary or metastatic malignant neoplasm affecting the head and neck. "One of the few studies focusing on head and neck cancer reported that SphK2 knockdown in human esophageal adenocarcinoma (OE33) reduced migration (but not invasion) in vitro." (PMID 24970177, 2013). "The function of Sphk2 in head and neck cancer has not been widely examined." (PMID 24970177, 2013).
head and neck squamous cell carcinoma (1 paper, 2025). A squamous cell carcinoma that arises from any of the following anatomic sites: lip and oral cavity, nasal cavity, paranasal sinuses, pharynx, larynx, and salivary glands. "Head and neck squamous cell carcinoma (HNSCC) exhibitsalterationsin sphingolipids, sphingosine kinase 2 (SK2), and microRNAs (miRNAs),including miR-205." (PMID 41476518, 2025).